TREM2 (triggering receptor expressed on myeloid cells 2)
Diseases named in the same sentence as TREM2 in open-access papers (continued):
Sharing a sentence is not in itself a finding about the gene and the disease.
colorectal cancer (25 papers, 2019 to 2025). A primary or metastatic malignant neoplasm that affects the colon or rectum. "Previous studies have encouragingly found that TREM2-deficiency and TREM2-blockade significantly induced preeminent anti-tumor responses in sarcoma, colorectal cancer, and mammary tumor models." (PMID 39075517, 2024). "Our findings are consistent with those of previous studies reporting a tumor-promoting role of TREM2 in other types of tumors, including sarcoma, colorectal cancer, and breast tumors." (PMID 39838454, 2025). "TREM2 has been shown to be involved in gastric, hepatocellular, and colorectal cancers, acting as a tumor promoter or suppressor." (PMID 36438899, 2022). "TREM2 deficiency was associated with reduced tumor growth in several transplantable models: MCA-derived sarcoma (MCA1956 and MCA206 cell lines), MC38 colorectal carcinoma, and PyMT breast cancer." (PMID 35746551, 2022). "In another 12 types of tumor, including colorectal cancer, lung cancer, stomach cancer, and lymphoma, TREM2 expression was related to MSI." (PMID 33679809, 2021). "Regarding colorectal carcinoma, our findings challenge those of previous research, which indicated that TREM2 is a potential prognostic biomarker, with expression downregulated in tumor tissues." (PMID 33679809, 2021). "Overall, our results identify TREM2 as a potential prognostic biomarker and therapeutic target for colorectal cancer." (PMID 31489935, 2019). "Here, we investigated TREM2 function for the first time in colorectal epithelial cancer cells and demonstrated that TREM2 is a novel tumor suppressor in colorectal carcinoma." (PMID 31489935, 2019). "In addition, increased TREM2 expression in TAMs promotes tumor progression in colorectal cancer, ovarian cancer, and TACE." (PMID 39135069, 2024). "Another extensive study based on the mouse model of Trem2–/– and wildtype mice in 3-methylcholanthrene-induced sarcoma, colorectal cancer and mammary tumor showed that anti-PD-1 immunotherapy is more effective in Trem2 deficient mice as compared to wild type mice." (PMID 37335084, 2023). "scRNA-seq in human and mouse colorectal cancer identified a population of C1QC+ TAMs, characterized by high levels of C1QA/B/C, TREM2, and MERTK expression, which were associated with potential recruitment and activation of T cells, phagocytosis, and better prognosis." (PMID 36240276, 2022). "More importantly, the authors showed ubiquitous abundance of TREM2+ macrophages across distinct human tumor samples, and that TREM2 expression inversely correlated with greater overall, and relapse-free survival in colorectal carcinoma and triple negative breast cancer patients." (PMID 34539650, 2021). "Thus, our findings provide the possibility that the TREM2-mediated suppression of the S phase cell cycle might be useful for therapeutic application in colorectal cancer." (PMID 31489935, 2019). "In colorectal cancer (CRC), TREM2+ TAMs contribute to immune evasion through suppression of dendritic cell recruitment and cytokine production." (PMID 40821795, 2025). "In colorectal cancer (CRC) and pancreatic cancer, high TREM2 expression was significantly negatively correlated with OS and RFS in patients, thus suggesting its potential oncogenic role." (PMID 40242752, 2025). "Studies have shown conflicting roles for TREM2 in different cancers; while TREM2 is protective in HCC, it correlates with poor survival in colorectal carcinoma and triple-negative breast cancer (TNBC)." (PMID 40385641, 2025).
colorectal cancer (continued). "Some studies have shown that TREM2 has an inhibitory effect on HCC and colorectal cancer through a variety of mechanisms." (PMID 36338707, 2022). "TREM2 deletion and anti-TREM2 mAb treatment were also shown to enhance anti-PD1 treatment in the sarcoma and colorectal carcinoma models (MCA1956 and MC38)." (PMID 35746551, 2022). "Furthermore, it establishes role of TRIP13 in colorectal cancer metastasis and identifies COL6A3, TREM2, SHC3, and KLK7 as its downstream targets." (PMID 33037736, 2020). "However, the function of TREM2 in colorectal cancer has not been clearly elucidated." (PMID 31489935, 2019).
lung carcinoma (25 papers, 2016 to 2025). "We further observed an MDM subset expressing inflammation and phagocytosis-associated genes (cluster 4; CCL18, IL18, C1QA and TREM2) and enriched for samples from patients with COVID-19 pneumonia, as well as samples from patients with lung carcinoma." (PMID 37291214, 2023). "In contrast, C1QC+ TAMs expressed the classical TAM-associated genes C1QA, C1QB, C1QC, APOE, and TREM2, which were previously reported in lung cancer." (PMID 37383234, 2023). "The age-associated loss of TREM2 in lung macrophages could thus account for compromised immunity to respiratory pathogens and increased lung cancer susceptibility observed in the aging population." (PMID 40804529, 2025). "Importantly, TREM2 deficiency inhibits lung cancer progression in vivo by reducing the population of M2-like TAMs and enhancing both the quantity and functionality of CD8+ T and NK cells." (PMID 39135069, 2024). "In addition, TREM2 KO monocyte-injected mice had smaller tumor volumes and weights and slower tumor growth than those of WT monocyte-injected mice, suggesting that TREM2 loss-of-function myeloid cells inhibit lung cancer progression." (PMID 39135069, 2024). "Although the role of the TREM2-DAP12 receptor complex in lung cancer progression is unknown, our findings elucidated that TREM2 or DAP12 deficiency inhibited lung cancer progression in vivo, suggesting that TREM2 affects lung cancer progression through the adaptor molecule, DAP12." (PMID 39135069, 2024). "TREM2 is identified as a key player in the regulation of tumor-associated myeloid cells, however, its specific role and immune regulatory mechanisms in lung cancer remains unclear." (PMID 39135069, 2024). "It is noteworthy that when TREM2 was knocked out or interfered with anti-TREM2 antibody, the recruitment and activation of NK cells were significantly promoted, thereby effectively inhibiting the occurrence and development of lung cancer." (PMID 40242752, 2025). "In glioblastoma (GBM) and lung cancer, TREM2 also regulates the tumor microenvironment (TME) by clearing apoptotic tumor cell debris through phagocytic mechanisms." (PMID 40242752, 2025). "Clinical investigations have revealed that the expression level of TREM2 on pulmonary macrophages is increased in lung cancer patients and is closely positively correlated with the pathological stage and lymph node metastasis of lung cancer." (PMID 40242752, 2025). "Despite its protective role against various pulmonary inflammatory diseases, TREM2 primarily promotes lung cancer progression." (PMID 40242752, 2025). "In non-small cell lung cancer (NSCLC), TREM2+ TAMs are specifically recruited to the tumor tissue of lung cancer through the CCL2-CCR2 axis." (PMID 40242752, 2025). "In lung cancer, TREM2+ monocyte-derived TAMs reduce NK cell activity by modulating interleukin (IL)-18/IL-18BP decoy interactions and IL-15 production." (PMID 39516356, 2024). "In the TME of lung cancer, immunohistochemical staining revealed elevated expression of TREM2 in intratumor tissues, resembling tumor-infiltrating macrophages." (PMID 39135069, 2024). "The interaction between TREM2 and galectin-3 was also confirmed in F4/80+ macrophages from patients with lung cancer using endogenous CO-IP experiments." (PMID 39135069, 2024). "Our findings revealed a high TREM2 expression in lung cancer macrophages, and abundant TREM2+ macrophages are enriched in the intratumor site in the presence of the CCL2-CCR2 chemotactic axis." (PMID 39135069, 2024). "In lung cancer, TREM2+ DCs exhibit immunosuppressive tumor-promoting properties, and TREM2+ mononuclear macrophages inhibit the accumulation and cytolytic activity of NK cells." (PMID 39135069, 2024). "To evaluate the expression profile of TREM2 in lung cancer, we initially analyzed peripheral blood mononuclear cells (PBMCs) of 35 lung cancer patients and 30 healthy volunteers." (PMID 39135069, 2024).
lung carcinoma (continued). "Further analyses between the TNM stage of lung cancer and TREM2 expression indicated increased TREM2 expression in the monocytes of patients with both early and advanced lung cancer." (PMID 39135069, 2024). "Genetic and pharmacological blockade of TREM2 and galectin-3 significantly inhibited lung cancer progression in subcutaneous and orthotopic cancer models by remodeling the tumor immune microenvironment." (PMID 39135069, 2024). "A novel therapeutic option was also based on the combination of anti-TREM2 antibodies and an NK cell-activating agent, resulting in the inhibition of tumor growth in a lung cancer model." (PMID 39516356, 2024). "TREM2+ macrophages are stably enriched in both early and late stages of lung cancer and have been defined as a pro-tumorigenic subset." (PMID 37187731, 2023). "To date, scRNA studies have revealed several new targets in lung cancer and brought new treatment options to immunotherapy such as TREM2+, SPP1+ and C1Q+ TAMs, which are associated with the malignant progression of lung cancer." (PMID 37187731, 2023). "Bone marrow derived DCs were induced to express TREM2 by culturing with conditioned media from 3LL lung cancer cells." (PMID 36119485, 2022). "In contrast, TAM-like macrophages expressed a set of genes (APOE, C1QA, C1QB and TREM2), which was found previously to be expressed in the TAMs of lung cancer." (PMID 36466840, 2022). "Lung cancer patients that responded to chemotherapy with a reduction of tumor burden displayed a decrease in TREM2 positive monocytes in the peripheral blood." (PMID 36119485, 2022). "The results show that TREM2 is highly expressed in most cancers, but present at low levels in lung cancer." (PMID 33679809, 2021). "TREM2 expression on lung macrophages was previously reported to be positively correlated with pathological stage in lung cancer." (PMID 33679809, 2021). "We discovered that compared to benign diseases, TREM-2 levels on MΦs were increased in lung cancer patients." (PMID 27102437, 2016). "Syk was responsible for TREM-2-mediated inhibitory signaling in lung cancer while Syk inhibitor restrained the IL-10 production of TREM-2+DC." (PMID 27102437, 2016). "On the other hand, the level of TREM-2 on pulmonary MΦs positively correlated with the pathological staging of lung cancer." (PMID 27102437, 2016). "This indicated that the expression of TREM-2 significantly increased in lung cancer patients compared to that of the healthy controls, and that in pulmonary MΦs had a positive correlation with pathological TNM staging of lung cancer." (PMID 27102437, 2016). "In addition, TREM2+ macrophages diminish the recruitment and cytolytic activity of NK cells by disabling IL-18 signaling in lung cancer." (PMID 39838454, 2025). "In the lung cancer mouse model, the expression of TREM2 in pulmonary CD11c+ DCs is increased." (PMID 40242752, 2025). "The number of TREM2+ TAMs is correlated with unfavorable survival or with a worse response rate to PD-1-based immune checkpoint inhibitors in patients with colorectal cancer, lung cancer, hepatocellular carcinoma, or melanoma." (PMID 39516356, 2024). "Moreover, the immunofluorescence results showed a clear and abundant population of cells co-expressing CD68 and TREM2 in human lung cancer than that in healthy lung." (PMID 39135069, 2024). "Consistent with previous results, TREM2 expression was higher in monocytes of lung cancer." (PMID 39135069, 2024). "We found that TREM2 was strongly associated with CCL2, CCL3, CCL13, and CCL17 in lung cancer." (PMID 39135069, 2024). "Similarly, in mouse lung cancer models, TREM2 expression was upregulated in both lung-infiltrating macrophages and splenic monocytes in tumor-bearing mice, which is consistent with observations in humans." (PMID 39135069, 2024). "Moreover, EGFR has been associated with high TREM2+TAM infiltration, advanced tumor progression and inferior prognosis in lung cancer patients." (PMID 38515213, 2024).
lung carcinoma (continued). "TREM2 has been reported to promote macrophage polarization from M1 to M2 via the NF-κB/CXCL3 and JAK-STAT pathways, and in lung cancer, TREM2+ macrophages were associated with a lack of NK cells and their dysfunction." (PMID 39776914, 2024). "However, the upstream regulators of TREM2 in TAMs during the immune response to lung cancer need to be further elucidated." (PMID 39135069, 2024). "Collectively, these findings confirmed that the CCL2-CCR2 chemotactic axis may contribute to the increase in TREM2+ macrophages in lung cancer." (PMID 39135069, 2024). "Moreover, there was a higher expression of TREM2 observed in patients with advanced lung cancer compared to those with early-stage disease." (PMID 39135069, 2024). "Additionally, lung cancer patients that underwent surgical tumor resection, and thus had a reduced tumor burden, also displayed a decrease in TREM2 positive monocytes in the peripheral blood." (PMID 36119485, 2022). "Furthermore, TREM2 expression on macrophages in lung cancer patient samples increased with both pathological staging of disease as well as degree of lymph node metastasis." (PMID 36119485, 2022). "More importantly, efficient therapy obviously reduced its expression, implying that TREM-2 may be a valuable marker for assessment of the efficacy of lung cancer therapy." (PMID 27102437, 2016). "Simultaneously, administration of anti-TREM-2 mAb in the lung cancer-bearing mice 7 days after tumor transplantation, depleting in vivo TREM-2, also, could not prolong the survival of tumor-bearing mice." (PMID 27102437, 2016). "Surprisingly, we found that TREM-2 could be detected on the monocytes of peripheral blood from both, patients with lung cancer and healthy controls, also on the MΦs of lung tissues." (PMID 27102437, 2016). "Furthermore, TREM2+DCs significantly suppress T cell proliferation in lung cancer." (PMID 40670983, 2025). "Surprisingly, we found that the expression of TREM-2 was markedly decreased in the patients with PR, while that was unchanged or even elevated in the patients with SD and PD, suggesting that TREM-2 may be a valuable index for estimating the efficacy of lung cancer chemotherapy." (PMID 27102437, 2016). "Triggering receptor expressed on myeloid cells-2 (TREM2) is expressed on TAMs and promotes immunosuppressive microenvironment formation and tumorigenesis in lung cancer, highlighting its potential as an immunotherapy target." (PMID 41417432, 2025). "In vivo, combination therapy with TREM2 knockout and the galectin-3 inhibitor GB1107 substantially inhibited lung cancer progression." (PMID 39135069, 2024). "The correlation analyses between TREM2 and TILs in lung cancer performed using the TIMER 2.0 website (cistrome.org), showed that TREM2 expression exhibited a strong correlation with mononuclear macrophages." (PMID 39135069, 2024). "Moreover, TREM2 inhibited NK cell-mediated secretion of anti-tumor molecules, including granzyme B and perforin, which was consistent with the previous findings that TREM2+ mononuclear macrophages suppressed NK cell accumulation and cytolytic activity in lung cancer." (PMID 39135069, 2024). "We found that the number of TREM-2+monocytes in peripheral blood and the mean fluorescence intensity (MFI) of its expression significantly increased in the lung cancer patients and tumor-bearing mice compared to that in healthy controls." (PMID 27102437, 2016). "In vivo experiments have observed that adoptive transfer of TREM2+ DCs can accelerate tumor growth in lung cancer-bearing mice but does not significantly affect their survival." (PMID 40242752, 2025). "In summary, our findings elucidate that elevated TREM2 expression is correlated with increased infiltration of immunosuppressive M2-like TAMs and suppression of intratumoral CD8+ T and NK cell responses in lung cancer." (PMID 39135069, 2024).
lung carcinoma (continued). "Notably, combination therapy with TREM2 knockout and the galectin-3 inhibitor GB1107 substantially inhibited lung cancer progression in vivo by decreasing tumor-infiltrating M2-like macrophages and increasing antitumor CD8+ T and NK cells." (PMID 39135069, 2024). "Notably, TREM2 knockout combined with the galectin-3 inhibitor GB1107 substantially inhibited the immunosuppressive effect of M2-TAMs and enhanced T/NK cell-mediated anti-tumor effects, improving the efficacy of lung cancer therapy." (PMID 39135069, 2024). "Also, adoptive transfer of this TREM-2+DCs accelerated the tumor growth rather than jeopardized survival in lung cancer-bearing mice." (PMID 27102437, 2016). "In conclusion, these results indicate that TREM-2 might act as a negative immuno-regulatory molecule through Syk pathway in an IL-10 dependent manner and partially predicts prognosis in lung cancer patients." (PMID 27102437, 2016). "TREM-2+DCs could accelerate tumor growth of lung cancer-bearing mice, but did not exhibit any effect on the survival of the orthotopic tumor models." (PMID 27102437, 2016). "In conclusion, we have shown that TREM-2 might act as a negative immuno-regulatory molecule through Syk pathway in an IL-10 dependent manner, and partially predict prognosis in patients with lung cancer." (PMID 27102437, 2016). "Hence, we suggest that TREM-2 might act as a negative immune regulator in lung cancer." (PMID 27102437, 2016).